SPHK1 (sphingosine kinase 1)
Diseases named in the same sentence as SPHK1 in open-access papers (continued):
Sharing a sentence is not in itself a finding about the gene and the disease.
prostate carcinoma (54 papers, 2009 to 2025). A carcinoma that arises from epithelial cells of the prostate gland. "In the present study we found that SphK1/2 dual inhibition by SKI-178 caused Akt-mTOR inactivation in prostate cancer cells." (PMID 37604912, 2023). "Various cancer tissues, including prostate cancers, have a high expression of SPHK-1, which is associated with shorter survival." (PMID 36139362, 2022). "Nonetheless, aberrant SphK1 isoform expression has been causally associated with prostate cancer therapy resistance in preclinical laboratory experiments." (PMID 36532885, 2022). "Resistance to camptothecin and docetaxel in PC-3 and LNCaP prostate cancer cells, respectively, is associated with stimulation of SphK1 activity." (PMID 25109605, 2014). "Moreover, GNE-493 downregulated Sphingosine Kinase 1 (SphK1), causing ceramide accumulation in primary prostate cancer cells." (PMID 35296639, 2022). "The SphK1/HIF‐1α signaling cascade has emerged as a central regulator of the anticancer effects of chrysin in hypoxia‐induced PC‐3 prostate cancer cells." (PMID 41427031, 2025). "The protein expression of both SphK1 and SphK2 was upregulated in prostate cancer tissues of three representative patients (“Patient-1/-2/-3”)." (PMID 37604912, 2023). "The potential effect of the SphK1/2 dual inhibitor on other prostate cancer cells was examined as well." (PMID 37604912, 2023). "Significantly, shRNA-induced silencing of SphK1/2 not only mimicked SKI-178-induced actions in prostate cancer cells." (PMID 37604912, 2023). "Together, targeting SphK1/2 by SKI-178 potently inhibited prostate cancer cell growth in vitro and in vivo." (PMID 37604912, 2023). "Sphingosine kinases (SphK), including SphK1 and SphK2, are important enzymes promoting progression of prostate cancer." (PMID 37604912, 2023). "As demonstrated, the mRNA expression of both SphK1 and SphK2 was significantly elevated in human prostate cancer tissues (“T”) from 10 different CRPC patients (tissues were provided by Dr. Mi)." (PMID 37604912, 2023). "Contrarily, ectopic overexpression of SphK1 and SphK2, by lentiviral constructs, further increased promoted primary prostate cancer cell growth in vitro and in vivo." (PMID 37604912, 2023). "Overexpression of SphK1 in prostate cancer is correlated with cancer grade and poor overall survival." (PMID 37604912, 2023). "The Cancer Genome Atlas (TCGA) database was first consulted to examine SphK1/2 expression in human prostate cancer." (PMID 37604912, 2023). "FTY720 single treatment also induced prostate cancer cell apoptosis by inhibiting SphK1 and inducing ceramide production." (PMID 37604912, 2023). "Ectopic overexpression of SphK1 and SphK2, by lentiviral constructs, promoted primary prostate cancer cell proliferation and migration." (PMID 37604912, 2023). "Here the TCGA database results and results from local tissues demonstrated that that both SphK1 and SphK2 are upregulated in human prostate cancer tissues." (PMID 37604912, 2023). "Conversely, SphK1 inhibition significantly augmented androgen deprivation-induced anti-prostate cancer cell activity." (PMID 37604912, 2023). "Bioinformatics analyses and results from local tissues demonstrated that that both SphK1 and SphK2 are upregulated in human prostate cancer tissues." (PMID 37604912, 2023). "The number of SphK1 transcripts in the prostate cancer tissues (“Tumor”) was significantly higher than that in the normal prostate tissues (“Normal”)." (PMID 37604912, 2023). "The lentiviral SphK1-overexpressing construct and the lentiviral SphK2-overexpressing construct were co-transduced to pCan1 primary prostate cancer cells, and stable cells were established after selection: “oe-SphK1+oe-SphK2” pCan1 cells." (PMID 37604912, 2023). "They concluded that mechanistically, melatonin inhibits HIF-1α stabilization and nuclear translocation in prostate cancer cells via inactivation of the SPHK-1 and Akt/GSK-3β, culminating in the demonstrated anti-angiogenic activity." (PMID 37191417, 2023).
prostate carcinoma (continued). "As shown, in the pCan-2 primary prostate cancer cells and established lines (PC-3 and LNCaP), the SphK1/2 dual inhibitor induced significant apoptosis activation, evidenced by significantly increased TUNEL-positive nuclei ratio." (PMID 37604912, 2023). "When combining all 10 sets of tissue blotting data, we found that SphK1 and SphK2 protein upregulation was significant in the local prostate cancer tissues." (PMID 37604912, 2023). "We here discovered that SphK1 protein downregulation and ceramide accumulation, independent of Akt-mTOR inactivation, were also important for prostate cancer cell death by GNE-493." (PMID 35296639, 2022). "In this study, the SPHK-1/HIF-1α pathway was identified as a potential therapeutic target for aggressive prostate cancer treatment." (PMID 36139362, 2022). "SphK1 is overexpressed and/or overactivated in prostate cancer, serving as an important diagnosis marker and therapeutic target." (PMID 35296639, 2022). "In the hormone-independent PC3 prostate cancer cell line, melatonin was able to inhibit sphingosine kinase 1 (SPHK1) and the Akt/glycogen synthase kinase-3β signaling, therefore impairing the stimulation of HIF-1α." (PMID 34209857, 2021). "Since then, other studies have shown the sensitization to docetaxel by SPHK1 inhibition in docetaxel-resistant prostate cancer cells." (PMID 35004331, 2021). "SPHK1 expression and S1P formation were highly elevated in a variety of tumors such as ovarian, breast, lung, colorectal, and prostate cancers, and hepatocellular carcinoma." (PMID 34502095, 2021). "Inhibitors of SPHK1 are used in ongoing clinical trials to sensitize epithelial ovarian and prostate cancer cells to various chemotherapeutic drugs, e.g., gemcitabine." (PMID 33660008, 2021). "There is a body of evidence for SPHK1 overexpression in a variety of solid cancers, e.g., prostate cancer, colorectal cancer and non-small-cell lung cancer." (PMID 33660008, 2021). "Increased circulating plasma levels of S1P and increased activity of SphK1 correlated significantly with both the grade diagnosis of prostate cancer as well as the prognosis." (PMID 32528896, 2020). "Reduced degradation of S1P in prostate cancer was paralleled by increased enzymatic activity of SphK1 in cancer tissues, which suggests that S1P metabolism in prostate cancer is shifted towards the S1P production." (PMID 32456134, 2020). "In prostate cancer patients, levels of both S1P and (sphingosine kinase 1) SphK1 have been identified as highly sensitive and specific biomarkers." (PMID 32528896, 2020). "Crataegus Pinnatifida Schneider ethanol extract decreased cell growth, HIF-1α and sphingosine kinase-1 (SPHK-1) in hypoxia-induced human prostate cancer DU145 cells." (PMID 31261861, 2019). "CPE decreased the abundance of HIF-1α and sphingosine kinase-1 (SPHK-1) in hypoxia-induced prostate cancer DU145 cells." (PMID 28165392, 2017). "We have recently discovered a new molecular mechanism of prostate cancer docetaxel chemoresistance mediated by the mammalian target of rapamycin (mTOR)/sphingosine-kinase-1 (SK1) pathway." (PMID 28615679, 2017). "More recent attention has been focused on the human SphK isoforms, especially since the discovery that androgen independent prostate cancer cells expressing hSphK1b isoform are refractory to SphK1 inhibitors." (PMID 28415564, 2017). "Previous studies have shown the involvement of the proteasome in the regulation of hSphK1, where novel inhibitors of SphK1-S1P activity induced the proteasomal degradation of this protein in prostate cancer cell lines." (PMID 28415564, 2017). "Silencing SphK1 expression in combination with increased SPL expression has been shown to decrease SIP content in prostate cancer cells, thus making them more sensitive to anticancer treatment." (PMID 29156544, 2017). "Here, we demonstrate that pristimerin inhibits HIF-1α via the SPHK-1 signaling pathway in a prostate cancer cell lines." (PMID 27581969, 2016).
prostate carcinoma (continued). "Our previous data showed a critical role of a lipid kinase sphingosine kinase 1 (SK1) in prostate cancer chemoresistance, and introduced the concept of SK1 as a “sensor” to anticancer therapies." (PMID 27821815, 2016). "Recently, in prostate cancer, an inverse relationship between expression of SPHK1 and SGPL1 was noted and down regulation of SGPL1 increased production of S1P and was associated with resistance to docetaxel." (PMID 26493335, 2015). "(S)-FTY720 vinylphosphonate inhibits and reduces the expression of SPHK1 15,16,101,102, resulting in apoptosis of prostate cancer cells 101 and human pulmonary smooth muscle cells." (PMID 26171944, 2015). "Recently, Brizuela and coworkers reported that SphK1 expression was upregulated whereas SPL expression was downregulated in prostatic cancer." (PMID 24468113, 2014). "This is supported by the observation that circulating S1P levels were reduced in prostate cancer patients when compared to control subjects or patients with benign hyperplasia, despite the reported up-regulation of SPHK1 in prostate cancer specimens." (PMID 24970218, 2014). "Not only did Sphk1 overexpression protect prostate cancer cells from green tea and wine polyphenol-induced death, but green tea and polyphenol treatment down-regulated SphK1 activity." (PMID 24970177, 2013). "In prostate cancer, resveratrol, epigallocatechin gallate, and polyphenols from green tea or grapevine extract (vineatrol) suppressed SphK1 protein expression in prostate PC-3 cells, with the greatest effects seen one to three days after treatment." (PMID 24970177, 2013). "It has been reported that the upregulation of SPHK1 impairs the effectiveness of chemotherapy in human PC-3 and LNCaP prostate cancer cell lines." (PMID 20846391, 2010). "Sphingosine kinase-1 (SphK1) is an oncogenic lipid kinase notably involved in response to anticancer therapies in prostate cancer." (PMID 19956567, 2009). "Further supporting this uncovered role for SphK1 during the transition to the hormone-refractory state, immunohistochemical studies of prostate cancer human samples showed for the first time that CgA positive-NE cells co-expressed SphK1." (PMID 19956567, 2009). "We report the first evidence that androgen deprivation induces a differential effect on SphK1 activity in hormone-sensitive prostate cancer cell models." (PMID 19956567, 2009). "Here, we explored the role of SphK1 in the regulation of androgen-dependent prostate cancer cell growth and survival." (PMID 19956567, 2009). "Here, we explored the potential role of SphK1 in the androgen-controlled cell growth and survival of the hormone-sensitive LNCaP prostate cancer cell model." (PMID 19956567, 2009). "In this study, we explored the potential role of SphK1 in the regulation of androgen-dependent cell growth and survival in the hormone-sensitive LNCaP prostate cancer cell model." (PMID 19956567, 2009). "Recently, we found SPHK1 promotes prostate cancer metastasis and neuroendocrine prostate cancer (NEPC) development in which FTY720 (Fingolimod), an FDA-approved SPHK1 inhibitor for multiple sclerosis, exhibits significant therapeutic efficacy using pre-clinical NEPC xenograft models." (PMID 39284838, 2024). "SphK1/2 inhibition by SKI-178 suppresses prostate cancer cell growth in vitro and in vivo." (PMID 37604912, 2023). "The expression of SphK1/2 in local prostate cancer tissues was examined as well." (PMID 37604912, 2023). "Interestingly, ectopic overexpression of SphK1 and SphK2 further increased Akt-mTOR activation in primary prostate cancer cells." (PMID 37604912, 2023). "LPS induced SphK1 S225 phosphorylation in a Toll-like receptor 4 (TLR4)-dependent manner, causing the translocation of SphK1 to plasma membrane, leading to S1P production and ERK1/2 activation, which were required for prostate cancer cell invasion and metastasis." (PMID 37604912, 2023). "Targeting SphK1/2 by SKI-178 induced significant anti-prostate cancer activity." (PMID 37604912, 2023).
prostate carcinoma (continued). "Indeed we discovered that Akt-mTOR-independent mechanisms by GNE-493, including ROS production and oxidative injury, programmed necrosis, SphK1 downregulation, and ceramide accumulation, were also important in mediating prostate cancer cell death." (PMID 35296639, 2022). "It has been shown that circulating S1P contents and erythrocyte SphK1 activity could be novel and efficient biomarkers for the early detection of prostate cancer." (PMID 35296639, 2022). "Although SphK1 inhibitors have been successful in increasing chemosensitivity, there are examples demonstrating discriminatory chemosensitivity depending on the expression of the two major SphK1 isoforms in hormone-dependent and independent prostate cancer cell lines." (PMID 36532885, 2022). "SphK1 is a key player in carcinogenesis and the development of prostate cancer." (PMID 35296639, 2022). "Similarly, high SphK1 expression is associated with prostate cancer chemotherapy resistance, and sensitivity to hormone-resistant prostate cancer cells can be restored by inhibiting the SphK pathway." (PMID 36532885, 2022). "Furthermore, melatonin inhibits the accumulation of HIF-1α through suppressing the formation of ROS and the sphingosine kinase 1 (SPHK1) pathway in prostate cancer cells under hypoxic conditions." (PMID 33789681, 2021). "In this regard, knockdown of Sphingosine kinase 1 (SK1) was associated with downregulation of NSUN2 in breast and prostate cancer cells, suggesting that pharmacological inhibitors of SK1 could potentially benefit cancers with overexpressed NSUN2." (PMID 32708015, 2020). "The combination of SPL-enforced expression with SphK1 may be a silencing strategy that decreases S1P content in the prostate, which may result in increasing the sensitivity of prostate cancer cells to anticancer therapies." (PMID 29156544, 2017). "Similarly, Pyne and colleagues demonstrated differences in the treatment response in prostate cancer depending on enhancement of specific SphK1 isoform expression." (PMID 28869494, 2017). "We assessed whether pristimerin suppresses hypoxia-induced HIF-1α and SPHK-1 in several prostate cancer cell lines (PC-3, DU145, and LNCaP)." (PMID 27581969, 2016). "Furthermore, FTY720 has been reported to be a sphingosine kinase 1 inhibitor that reduces the expression of androgen receptor in prostate cancer cells." (PMID 26023836, 2015). "A study on prostate cancer cells has shown that FTY720 could moderately elevate cellular ceramide levels by directly inhibiting SPHK1." (PMID 25050888, 2014). "Thus, the authors propose that polyphenols directly regulate ERK1/2, in turn control PLD, which then manipulates the SphK1/S1P pathway to affect tumor growth in prostate cancer." (PMID 24970177, 2013). "In addition to expression, it was also reported that there was increased enzymatic activity of SphK1 in prostate cancer that directly correlated with the higher PSA expression." (PMID 23028939, 2012). "Indeed, the expression level of SPHK1 has been found to be frequently upregulated in various tumor types, including glioblastoma multiforme, intestinal adenoma, acute erythroleukemia, prostate cancer, colon cancer, and gastric cancer." (PMID 20846391, 2010). "SphK1/2 inhibition could induce apoptosis activation in prostate cancer cells." (PMID 37604912, 2023). "Similarly, lipopolysaccharide was shown to stimulate prostate cancer cell invasion, progression, and metastasis via SPHK1/S1PR4/matriptase signaling, indicating that S1PR4 signaling is crucial for the progression of prostate cancer mediated by bacterial infection." (PMID 35565311, 2022). "Balanocarpol induced down-regulation of SphK1 activity and expression in prostate cancer cells, the mechanism may involve changes in the SphK1 protein turnover, as has been shown for other SphK1 inhibitors to induce ubiquitin proteasomal degradation of SphK1 or changes in gene promoter activity." (PMID 34737701, 2021).
prostate carcinoma (continued). "Thus, in this study, we evaluated whether the inhibition of HIF-1α by CA involves the SPHK-1 pathway under hypoxia in the DU145 human prostate cancer cell line." (PMID 28165392, 2017). "Similarly, decreased levels of SPHK1 under chemotherapy were also observed in prostate cancer cell lines, which was further corroborated by in vivo studies with mice that showed SPHK1 inhibition, smaller tumor volume, and reduced occurrence and number of metastases." (PMID 29186783, 2017). "To investigate whether the decrease in HIF-1α expression by CA in hypoxic prostate cancer cells involves in the SPHK-1 pathway, AKT, and GSK-3β and to delineate the downstream signaling mechanism of SPHK-1, we performed western blot analysis and SPHK-1 activity assay." (PMID 28165392, 2017). "On the other hand, anticancer treatments (chemotherapies, radiation therapy) trigger down-regulation of SphK1 activity in various cancer cell and animal models suggesting that SphK1 could act as a “sensor” to anticancer therapies particularly in prostate cancer." (PMID 19956567, 2009). "By virtue of the uncovered role of SphK1 in mediating the transition from androgen-dependent to androgen refractory state, the pharmacological inhibition of SphK1 and its downstream signaling could represent a viable strategy to prevent or delay the progression to hormone-refractory prostate cancer." (PMID 19956567, 2009). "It is tempting to speculate that the SphK1 activation upon chronic androgen deprivation may serve as an adaptive mechanism allowing prostate cancer cells to survive in androgen-depleted environment, as SphK1 is a well described pro-survival pathway via the effects of sphingosine 1-phosphate." (PMID 19956567, 2009). "We also compared the anti-prostate cancer cell activity between SKI-178 and other SphK1/2 inhibitors, including the SphK1 inhibitor PF-543 and the SphK2 inhibitor ABC294640." (PMID 37604912, 2023). "Under hypoxic situations in prostate cancer cells, melatonin suppresses the generation of HIF-1 by preventing the production of ROS and the sphingosine kinase 1 (SPHK1) pathway." (PMID 36759799, 2023). "Since SKI-178 is a novel and highly efficient SphK1/2 dual inhibitor, we next analyzed SphK1/2 expression and activity in SKI-178-treated prostate cancer cells." (PMID 37604912, 2023). "K6PC-5, the SphK1 activator, or supplement with S1P, largely ameliorated SKI-178-induced cytotoxicity in primary prostate cancer cells." (PMID 37604912, 2023). "Akt-mTOR inactivation, SphK1 downregulation, ceramide level increase, and oxidative injury were detected in GNE-493-treated prostate cancer xenograft tissues." (PMID 35296639, 2022). "However, the diagnostic value of circulating Sphk1/S1P, unlike miRNAs, needs further investigation since there has no acceptable reference levels, although it has been reported that circulating S1P and erythrocyte Sphk1 activity could be a biomarkers for early prostate cancer detection." (PMID 28991193, 2017). "Our study showed that SPHK-1 and HIF-1α accumulations began to increase after 30 min of hypoxia exposure in PC-3 prostate cancer cells compared with the normoxia, which is consistent with previous studies." (PMID 27581969, 2016). "SKI-178 largely inhibited SphK activity and induced ceramide production, without affecting SphK1/2 expression, in prostate cancer cells." (PMID 37604912, 2023). "Therefore, SKI-178 was invalid in SphK1/2-silenced cells, supporting that SphK inhibition should be the primary mechanism of SKI-178-induced cytotoxicity in prostate cancer cells." (PMID 37604912, 2023). "The strong expression of SphK1 in tissues was confirmed by the quantification of SphK1 enzymatic activity, which we originally reported in prostate cancer patients, using 12 osteosarcoma compared to 10 nontumoral bone samples." (PMID 35158767, 2022).